MYC (MYC proto-oncogene, bHLH transcription factor)
Diseases named in the same sentence as MYC in open-access papers (continued):
Sharing a sentence is not in itself a finding about the gene and the disease.
tumor (continued). "In addition to MYC, hypoxia-inducible factor (HIF)-1α is another critical transcription factor responsible for glycolysis in tumor cells short of oxygen supply." (PMID 32651356, 2020). "To evaluate if cytokines secreted by cancer cells mediate MYC and Twist1 driven macrophage recruitment and polarization, we evaluated the impact of tumor cell derived conditioned media on non-polarized macrophage cell lines." (PMID 31933479, 2020). "We also found that loss of PRKD3 reduced the rate of the cell proliferation in vitro and tumour growth in vivo, whereas ectopic (over)expression of PRKD3, ERK1 or c‐MYC in the PRKD3‐knockout breast cells reverse the suppression of the cell proliferation and tumour growth." (PMID 31944568, 2020). "Moreover, we detected eight gene amplifications in six different tumor specimens, including CCND2 (n = 3), FLT3 (n = 3), FGFR1, and MYC." (PMID 33322358, 2020). "In striking contrast, all c-MYC/CRE injected Brg1f/f mice appeared to be healthy with no signs of tumor development." (PMID 32019910, 2020). "Conditioned media from TAMs isolated from MYC/Twist1-HCC but not MYC-HCC increased the invasiveness of both MYC- and MYC/Twist1-HCC tumor cells in vitro." (PMID 31933479, 2020). "Likewise, it appeared that the levels of MYC and MCL1 were much higher in NSCLC tumor cells relative to adjacent normal lung cells, and CycT strongly decreased their levels in tumor cells." (PMID 30723259, 2019). "According to our study, expression levels of LPCAT1 were strongly associated with amplifications of HER2 and MYC, negative ER and PR status and PTEN deletions, which are all linked to adverse tumor features and poor patient outcome." (PMID 31533087, 2019). "This study also identified c-MYC as an SYK-promoted gene that in turn could activate transcription of MALAT1, resulting in tumor growth." (PMID 31275859, 2019). "We conclude that in T-ALL, MYC-driven overexpression of TET1 contributes to tumor cell-specific 5mC and 5hmC patterns and thus gene expression programs that are important for enhanced global protein synthesis and tumor cell proliferation." (PMID 31266538, 2019). "Another antagonist of MYC is the tumor suppressor P19ARF that can block activating functions of MYC by direct binding, without affecting its expression." (PMID 30836996, 2019). "Furthermore, we recently reported that MYC deregulates the expression of methylation modifiers, DNMT3B and DNMT1, essential for tumor maintenance." (PMID 31266538, 2019). "However, inhibiting MYC-MAX interaction in vivo has been limited by fast metabolism, poor potency, resistance mechanisms, and poor tumor penetrability of these small molecule inhibitors." (PMID 30076412, 2019). "Although the statistical significance of the MYC copy number gain did not come from the multivariate analysis, it cannot be concluded at this time because of small number of tumor-specific death in the TCGA dataset." (PMID 31848373, 2019). "In ER− tumours that received no chemotherapy, MYC overexpressed tumours with low ATM protein levels had the worst survival." (PMID 30746633, 2019). "This study demonstrates for the first time that the MYC oncogene deregulates the expression of TET methylcytosine dioxygenases and thereby global DNA (hydroxy)methylation and gene expression programs to maintain tumor cell proliferation." (PMID 31266538, 2019). "Furthermore, in consistent with our in vitro results, both decreased levels of MYC and induction of apoptosis were observed in JQ1 treated tumor xenografts by IHC staining." (PMID 30770740, 2019). "Notably, MYC, SUZ12, and KRAS can also be suppressed by 5‐Aza in other manners, especially with the involvement of miRNAs in different tumor microenvironments." (PMID 30791232, 2019). "Moreover, METTL3 or IGF2BP2 expression positively correlated with the SOX2 downstream genes CCND1, MYC, and POU5F1 in our independent cohort of paired CRC tumor and adjacent normal tissues from SYSUCC." (PMID 31230592, 2019).
tumor (continued). "Studies in a pancreatic mouse model have demonstrated that MYC amplification stimulates the production of the potent proinflammatory cytokines IL-1β and CCL5, leading to the recruitment of pro-tumoral mast cells in tumor tissue." (PMID 31831007, 2019). "The p27Super genotype delays tumor onset in both LMP2A/λ-MYC and λ-MYC mice." (PMID 30992353, 2019). "Unlike the vague role of MYCN in FA metabolism, MYC was thought to play a key role in accelerating FA and cholesterol metabolism for sustainable tumor cell growth." (PMID 31856871, 2019). "Further, PIK3CA, MYC, HIF1A and other genes with frequent alterations in primary tumours are known to dysregulate cellular metabolism by increasing the rate of glycolysis while reducing the rate of aerobic respiration; a phenomenon referred to as the Warburg effect." (PMID 31754644, 2019). "IPA-derived relational networks reflect the possible roles of known oncogenes, e.g., MYC and HDGF (REF: PMID 27543492), overexpressed in B-raf V600E_high samples, and tumor suppressors, e.g., PML and toll-like receptors (PMID: 30127747, 29416846), downregulated in B-raf V600E_high samples." (PMID 31835364, 2019). "Similarly, inactivation of MYC in T-ALL has previously been shown to shut down global protein synthesis eliciting cellular senescence and tumor regression." (PMID 31266538, 2019). "We conclude that the MYC oncogene upregulates TET1 while suppressing TET2 expression in T-ALL, and speculated whether TET function was essential for tumor maintenance." (PMID 31266538, 2019). "Importantly, we determined that BRD4 was dispensable for MYC expression in the most resistant cell lines and that MYC RNAi + BET bromodomain inhibition led to additive anti-tumor activity in the most resistant cell lines." (PMID 30846826, 2019). "Tumor onset was delayed in both LMP2A/λ-MYC/p27Super and λ-MYC/p27Super mice." (PMID 30992353, 2019). "In fact, genomic co-amplification of MYC and PVT1 has been reported in different types of tumor." (PMID 31781490, 2019). "In this context, we interrogated this question directly and tested the c-MYC-overexpressing MSC in vivo to assess whether an increase in stemness and high PDN characteristics observed in these cells would result in tumor growth incidence." (PMID 30836996, 2019). "For example, decapping enzyme Nudt3, a member of nudix hydrolase superfamily, promoting MCF7 cell migration and proliferation by modulating β6 and lipocalin-2 mRNA stability; Dcp2, the first discovered decapping enzyme, enhanced tumor cell growth by affected RAS and MYC mRNA stability." (PMID 31164795, 2019). "Furthermore, we identified a subset of oncogenic MYC targets regulated by NELFE, called NELFE-dependent MYC targets (NDMTs), in HCC tumor tissue and have functionally validated these findings through in vitro studies." (PMID 30833661, 2019). "Among the tumor-related genes, the top amplified genes included ERBB2 (17q21), MYC (8q24), GNAS (20q13), EGFR (7p11), ZNF217 (20q13), CCNE1(19q12), NCOA3 (20q13), and CDK6 (7q21), and the most frequently deleted genes were CDKN2A (9p21), CDKN2B (9p21), KIT (4q12), SMAD4 (18q21), and FGFR1 (8p12)." (PMID 31541076, 2019). "While CR-31 treatment suppresses tumour growth in vivo, these tumours, collected 2 h after final treatment, do not exhibit a decrease in c-MYC protein levels." (PMID 31723131, 2019). "Additionally, microRNA replacement therapy for miR-145 in a model of colon carcinoma has been revealed to be efficient in reducing tumor growth in vivo with concomitant repression of ERK5 and c-MYC." (PMID 30901834, 2019). "Strikingly, tumor onset in the LMP2A/λ-MYC/p27Super mice was later than that in the λ-MYC mice and not significantly different from that in λ-MYC/p27Super mice." (PMID 30992353, 2019). "As the two common drivers of DHL, MYC and BCL2 cooperate in lymphomagenesis and tumor maintenance." (PMID 31752970, 2019).
tumor (continued). "Assessment of somatic copy number variants (focal homozygous deletions or ≥2-copy gain somatic copy number variants using a Log2 fold change of ≤−0.9 and ≥0.4) from the 24 WGS tumor/normal pairs revealed focal copy number gains in CFA 13 involving PDGFRA (29% WGS) and MYC (38% WGS)." (PMID 31341965, 2019). "Further, we demonstrate that co-targeting MYC together with BET bromodomain inhibition in cells in which JQ1 fails to suppress MYC expression leads to additive anti-tumor activity." (PMID 30846826, 2019). "In turn, CIP-2a promotes tumorigenesis and, in general, tumor progression by inhibiting the activity of protein phosphatase 2A (PP2A)—a prerequisite for the oncogenic transformation of human cells—and by stabilizing c-MYC in different tumors." (PMID 31001477, 2019). "All 3 oncogenes in 50 CRCs, except for MYC in one tumor and CDK4 in three tumors, were upregulated and 3 normal colonic physiological genes were downregulated, except for CD177 in one tumor, AQP8 in two tumors and GPX3 in three tumors." (PMID 31409279, 2019). "A total of 696 tumours were suitable for ATM and MYC protein expression analyses." (PMID 30746633, 2019). "A total of 793 tumours were suitable for ATR and MYC protein co-expression analyses." (PMID 30746633, 2019). "We previously demonstrated an S10A knock-in of p27Kip1 (p27S10A/S10A) that prevented S10 phosphorylation failed to significantly delay tumor onset in LMP2A/λ-MYC mice." (PMID 30992353, 2019). "All (100%) jaw BL tumours were positive for EBER-1 and 90.1% expressed MYC protein." (PMID 32180880, 2019). "Thus, different tumor super-enhancers have the opportunity to form through diverse mechanisms throughout this large TAD and can exploit the MYC CTCF site to interact with and activate MYC expression." (PMID 29641996, 2018). "Studies using mice totally lacking A1 also suggest that A1 contributes to tumour cell survival in the context of MYC overexpression." (PMID 29498802, 2018). "To determine the potential regulation of MYC in murine PDAC and NSCLC tumors treated with BAY 1238097, we generated two cell lines from each tumor type (PDAC: mPDAC 1.1 and mPDAC 1.2; NSCLC: MLT#1 and MLT#6) and treated them in vitro for 3 days with the compound." (PMID 29721157, 2018). "The mean MYC amplification ratio in PR negative tumors was 0.5 times higher than in tumor tissues that were PR positive; ER positive cases had slightly higher MYC amplification ratios than ER negative cases." (PMID 29523126, 2018). "In mouse models, inactivation of MYC dramatically halts tumor cell growth and proliferation, without invoking tumor escape pathways 1, 2, making targeting MYC an attractive approach for anticancer therapy." (PMID 30222246, 2018). "These alterations, alongside the cytokines and growth factors released by macrophages that will be lacking following CSF1R inhibition, result in reduced tumor cell proliferation and changes in a number of tumor cell intrinsic pathways (MYC, metabolism)." (PMID 29719257, 2018). "It is believed that the activation of MYC may be important for the pathogenesis of the disease to overcome the repressor effects of BLIMP1, and provide the tumour cells with a proliferative and survival advantage." (PMID 29518976, 2018). "The main possible drivers for this neoplasia were DICER1, NF1 and MYC." (PMID 29459759, 2018). "In vivo, using liver-specific inducible MYC transgenic mice fed MCD diet, blocking CPT with the pharmacological inhibitor perhexiline decreased apoptosis of intrahepatic CD4+ T cells and inhibited HCC tumor formation." (PMID 29795111, 2018).
tumor (continued). "First, to inhibit a background tumor from which the three subclones originated, HER2 inhibitor, MYC inhibitor, and AKT inhibitor might be used." (PMID 30296938, 2018). "Of these, prominent examples included amplifications targeting the epidermal growth factor receptor (EGFR) (7p11.2) and MYC (8q24.3) and deletions at 10q23.31, encompassing the PTEN tumour suppressor gene in cold tumours and JAK2 (9p24.1) amplifications in hot tumours." (PMID 30104673, 2018). "FISH validation data of MYC translocations were not available to tune LUMPY parameters and, as a result, intra- and (non-IGH) inter-chromosomal MYC translocations were called at a high false-positive rate (in every tumor and normal sample)." (PMID 29563506, 2018). "In the Eμ‐MYC/Vav‐BFL1 mice, these progenitor tumours were largely restricted to the thymus." (PMID 29498802, 2018). "NGS analysis of the two tumors showed an amplification of MYC with a copy number of 76 in the 2017 tumor, which was not present in the 2011 tumor, along with a significant mutant KRAS amplification." (PMID 30788462, 2018). "This suggests that repression of the expression of a subset of tumor suppressor miRNAs in T-ALL cells might be a result of NOTCH and MYC activation." (PMID 29435192, 2018). "In addition to genes that were also modulated in lSSc samples (i.e., MYC, AKT2, and PIM1), other genes involved in cell proliferation and also in tumor development were overexpressed." (PMID 29559981, 2018). "As genetic aberrations are rare events, it would be expected that if additional genetics events, in conjunction with expression of MYC, AKT and BCLXL would be required for tumor growth in vivo, then this would result in monoclonal tumors, and conversely, if not, tumors would be polyclonal." (PMID 29765548, 2018). "The ability of MYC and CXCL12/CXCR4 signaling to maintain a high glycolytic flux may also allow tumor cells to invade tissues with low-oxygen tension." (PMID 30202007, 2018). "By stabilizing c-MYC and MKI67 transcripts, IGF2BP1 enhances tumor cell proliferation and growth." (PMID 29954406, 2018). "In addition, CD133 depletion also suppresses tumor cell proliferation, colony formation, and the expression of stemness transcription factors including NANOG, OCT4, SOX2, and c-MYC." (PMID 29568348, 2018). "c-MYC is a transcription factor that regulates many basic cellular processes, such as cell proliferation, cell transformation, and apoptosis, and the deregulation of c-MYC plays a critical role in carcinogenesis and tumour progression." (PMID 29396413, 2018). "Our results suggest that expression of MYC and activated AKT together with inhibition of intrinsic apoptosis via expression of BCLXL would constitute sufficient conditions for tumor transformation of mature mouse T cells, based on the rapid kinetics and high frequency of the process." (PMID 29765548, 2018). "Previous reports studying gastric, colon and live cancers demonstrated that c-MYC could directly bind to the promoter region of CCAT1 to enhance expression of this lncRNA, facilitating tumor progression." (PMID 30190462, 2018). "Furthermore, we demonstrate regulation of MYC promoter activity by ALK in ALK+ cell lines and non-tumor NIH3T3 ectopically expressing EML4-ALK." (PMID 29507657, 2018). "Further, it inhibits MYC:MAX interaction, reduces proliferation and induces massive apoptosis in tumor tissue from a MYC-driven xenograft tumor model without severe side effects." (PMID 29968736, 2018). "Although MYC translocations or mutations are not common in AML, the activation of MYC by multiple tumor-driven genetic aberrations has been recognized as a major factor of leukemogenesis, providing the rationale to target MYC in AML." (PMID 29996811, 2018).
tumor (continued). "MYC is a key player in tumor development, but unfortunately no specific MYC-targeting drugs are clinically available." (PMID 29968736, 2018). "However, when we attempted this analysis using MYC-low or KAT2A-low subsets, the compartment calls were more dissimilar to both normal and tumour compartment calls than they were to each other." (PMID 28592290, 2017). "Here we first review the role of anabolic MYC and catabolic AMPK pathways in context of cancer and then discuss how the concomitant activity of both pathways in tumor cells may result in targetable synthetic lethal vulnerabilities." (PMID 28443281, 2017). "Several studies have shown that let-7 functions as a tumor suppressor miRNA by inhibiting the expression of growth promoting proto-oncogenes, such as RAS and MYC or by the destabilization of mRNA chaperones such as IMP-1/CRD-BP (coding region determinant-binding protein)." (PMID 29163823, 2017). "Pearson correlations on whole transcriptome centroids between MYC (n=4), VM (n=4) and VIM (n=4) mouse tumours and the TCGA KIRC and KIRP data revealed that VM and VIM tumours correlated most highly with TCGA KIRC tumours, while MYC tumours correlated more highly with TCGA KIRP tumours." (PMID 28593993, 2017). "The fact that MYC controls glutamine uptake and catabolism through transcription of SLC3a2, SLC5A1, SLC7A1, and GLS1 in tumor cells indicates that additional signaling events are involved in determining the target preference of MYC between tumor cells and activated T cells." (PMID 28245597, 2017). "In summary, the signaling pathways converging on MYC, AKT and HIF have the capacity to reprogram cell metabolism to fulfill the biomass needs of tumor growth by directing the biosynthesis of proteins, lipids and nucleotides while maintaining an adequate level of cellular ATP." (PMID 28969664, 2017). "Thereby it provides further evidence for the notion that both positive and negative transcriptional regulation is critical for MYC-driven tumor maintenance." (PMID 29100357, 2017). "A lack of staining was scored as negative, a tumor sample was regarded as strongly stained if at least 50% of the tumor cells exhibited strong MYC staining, and the remaining samples were regarded as intermediate." (PMID 29180625, 2017). "Together with that c-MYC was one of STAT3 target genes, and was essential for tumor angiogenesis, we wondered whether JAK/STAT3 signaling pathway was aberrant activated during the transition of NECs toward TECs." (PMID 29088816, 2017). "MYC functions can be antagonized by the interaction between MXD/MXI1 bHLHZip transcription factor proteins, which in turn suppress MYC mediated transformation and tumor growth." (PMID 28245597, 2017). "Unlike healthy cells, most tumor cells cannot switch off MYC expression in response to anti-proliferative signals from outside of the cell." (PMID 28443281, 2017). "While numerous MYC target genes have been identified in various tumor types, the lack of overlap makes it difficult to assign MYC’s oncogenic properties to a particular set of genes, suggesting alternative mechanisms." (PMID 29100357, 2017). "Specifically, DDC- or CCl4-treated c-MYC mice display tumors between 31 and 40 days, respectively, compared to non-treated c-MYC mice in which the tumor burden occurs at 183 days." (PMID 28422055, 2017). "MYC expression increased markedly when FOXO3A was silenced in SKM-1 cells, which could indicate that MYC is a downstream target of FOXO3A and that the tumor-suppressive properties of FOXO3A may be related to MYC inhibition." (PMID 29124072, 2017). "At face value, these data suggested that MYC is not essential for treatment response in KRAS mutant tumor cells." (PMID 28152508, 2017). "Neither the MYC nor MINA53 staining patterns were associated with the clinico-pathological parameters of age at surgery, gender, pT, pN, pM, tumor grade or patient’s survival (Chi-squared test)." (PMID 29180625, 2017).